FGFR1 (fibroblast growth factor receptor 1)
Diseases named in the same sentence as FGFR1 in open-access papers (continued):
Sharing a sentence is not in itself a finding about the gene and the disease.
tumor (continued). "The situation was similar for FGFR1: moderate-to-strong staining was associated with tumor location and higher grade in both the whole and the adult cohort, despite the lack of clinical associations in the pediatric cohort." (PMID 28468611, 2017). "In contrast, a noticeable expression of Fgfr1 splice variant was evident in all the murine tumor samples." (PMID 28460439, 2017). "Consistent with FGFR3 expression, FGFR1 immunostaining was significantly associated with a higher tumor grade (p < 0.05, Fisher’s exact test) and cerebral location (p < 0.01, Fisher’s exact test)." (PMID 28468611, 2017). "FGFR1 mutations were found in 6 % of thalamic gliomas (5 % and 9 % of low and high grade tumours respectively)." (PMID 27577993, 2016). "In Lum cancers, FGFR1 expression was associated with high tumor grade (p = 0.005), pN (p = 0.004) and pT stages (p = 0.001), large tumor size (p = 0.001), and the presence of LVI (p = 0.031)." (PMID 26673008, 2016). "Identification of this FGFR1 splice variant was verified in metastatic human BC cell lines and patient-derived tumor samples." (PMID 24618085, 2014). "For example, FGFR1 overexpression or a somatic activating mutation in the kinase domain has been found in tumor cells, leading to the examination of FGFR1 as an anti-cancer target." (PMID 23451204, 2013). "For the first time, our gene expression profiling experiment on archival tumour materials has identified upregulated FGFR1 expression to be associated with PC progression to the CR state." (PMID 21952621, 2011). "Sef loss was observed in 57% of tumours with weak or moderate levels of FGFR1 and also in 38% of tumours with strong FGFR1 expression (P=0.27)." (PMID 19888221, 2009). "Our results demonstrated that expression of seven alternative splice variant mRNAs (VEGFR1, VEGFR3, Met, RAGE, Tie1, FGFR1, and Kit) is present in multiple normal and tumor tissues." (PMID 18593464, 2008). "Finally, the FGF/FGFR1/NOTCH1 within RB1 variant group has a remarkably high ratio of inner‐tumor CD8+ T cell infiltration, non‐exhausted T cells, exhausted TCD8+PD‐1+LAG3− cells, and TRMCD8+CD69+CD103+cells." (PMID 40001320, 2025). "Furthermore, researchers are exploring the use of circulating tumor DNA and other liquid biopsy techniques to dynamically monitor FGFR1 mutations and treatment response over time." (PMID 40547805, 2025). "Interestingly, a multicenter Phase II study evaluating the effect of infigratinib another selective FGFR1-3 inhibitor, recently demonstrates over a year of disease control in patients with tumours harbouring FGFR1/3 point mutations or FGFR3-TACC3 fusions." (PMID 40467542, 2025). "FGFR1 mutations and their association with particular tumor groups." (PMID 40361492, 2025). "The abnormal activation of FGFR1 is mainly associated with its genetic amplification, mutations, fusions, and rearrangements and is generally associated with high tumor aggressiveness, resistance to hormone therapy, poor differentiation, and adverse clinical outcomes." (PMID 39590377, 2024). "Regarding molecular features, patients with KIAA1549-BRAF fusion have better outcomes, especially when the tumor is cerebellar, and those with FGFR1 mutations—especially those with FGFR1 pK656E point mutation—do worse, although the last study included a small number of both pediatric and adult LGGs." (PMID 39590171, 2024). "By studying key gene mutations such as PIK3CA and FGFR1, more precise treatments could be developed to address these complex tumor traits." (PMID 39457636, 2024). "Next-generation sequencing found that the tumor harbors an FGFR1 and a RAS mutation." (PMID 38903142, 2024). "Additionally, FGFR1 mutations contribute to angiogenesis and immune evasion within the tumor microenvironment, further facilitating tumor growth and metastasis, thus complicating disease management." (PMID 39590377, 2024).
tumor (continued). "KRAS mutation could upregulate the expression of PD-L1 in tumor cells by different mechanisms including improving the stability of PD-L1 mRNA, promoting ROS production and inducing FGFR1 expression in lung cancer." (PMID 38097680, 2023). "Nevertheless, we considered that the multifocal development hypothesis more likely because SL and mother tumor barely shared the mutation except FGFR1 mutation and the mutated genes types were completely different from each other." (PMID 36639714, 2023). "Finally, we observed that in 90% (9/10) of FGFR1MUT cases for which we had the information, FGFR1 mutation was clonal to H3-3A mutation with a similar variant allele frequency suggesting a role in the early steps of oncogenesis of these tumours." (PMID 38066305, 2023). "High FGFR1 expression in tumor tissues was associated with less favorable tumor characteristics; high histological grade (OR=1.86, 95% CI 1.00–3.44), high Ki67 proliferative index (OR=2.18, 95% CI 1.18–4.02) as well as tumors of Luminal B-like subtype (OR=2.56, 95%CI 1.29–5.06)." (PMID 37546410, 2023). "FGFR1 expression in tumor tissues was associated with less favorable tumor characteristics." (PMID 37546410, 2023). "The fair discrimination of tumours on the tSNE based on the type of the secondary MAPK mutation (i.e. BRAF vs. FGFR1) even suggests that this entity could be further subdivided." (PMID 38066305, 2023). "Notably, all samples harbored both mutation and focal amplification in the FGFR1 oncogene, resulting in an extraordinarily high expression, likely to be the main driver of this tumor." (PMID 34971484, 2022). "However, the fact that translocations and mutations of the FGFR1 gene lead to a constitutively activated FGFR1 protein in around 10% of tumours highlights the unique role of FGFR1 as an oncogene and its accountability during the arise of resistance." (PMID 35193394, 2022). "The paracrine action of bFGF, in stimulating local tumour‐associated angiogenesis via FGFR1, may be accompanied by rising levels of the growth factor within the sera of affected patients, the measurement of which has been used as a prognostic biomarker." (PMID 35152467, 2022). "However, orthotopically transplanted PANC1 cells deficient for FGFR1 generated smaller tumours compared to parental cells transduced with the empty vector, thus suggesting cell extrinsic effects of FGFR1 downregulation in this cell line." (PMID 35963908, 2022). "The different expression patterns encompassed genes related to the FGFR pathway, including FGFR1–4 receptors but also other oncogenic genes, which might be linked to tumor sensitivity to FGFRis." (PMID 35402233, 2022). "A patient with a papillary tumor of the pineal region (CNS WHO grade 2; patient 25) and mTOR pathway activation in Phospho-IHC potentially due to allelic loss of PTEN and FGFR1 amplification was treated with everolimus with resulting SD until tumor progression after nine months." (PMID 35864412, 2022). "For commonly occurring FGFR1-4 SVs and REs, we also describe their tumor type-specific association with TMB and the genomic comutational landscape, including significantly co-occurring and mutually exclusive (i.e. significantly likely to not co-occur) genomic alterations." (PMID 36462464, 2022). "We found the hotspot mutation N546K in FGFR1 in one tumor at diagnosis and relapse." (PMID 35488346, 2022). "Importantly, activation of epithelial FGFR1/2 by paracrine FGFs promotes tumor progression and induces EMT in vivo, which is associated with a switch of FGFR isoforms from IIIb to IIIc." (PMID 34830951, 2021). "FGFR1 mutations have also been implicated in tumor pathogenesis, as well as IDH1." (PMID 34069450, 2021). "After multivariate adjustment for the known prognostic factors Ki-67 and ENSAT tumor stage, FGFR1 remained significantly associated with recurrence-free survival (HR=6.10, 95%CI: 1.78 – 20.86, p=0.004) and FGFR4 with overall survival (HR=3.23, 95%CI: 1.52 – 6.88, p=0.002)." (PMID 34956100, 2021).
tumor (continued). "In these tumor subtypes, FGFR1 mutations occur in up to 20% of patients, and in rare cases may be germline events." (PMID 32164789, 2020). "Notably, a subset of RGNT (4/10, 40%) have copy-neutral loss of heterozygosity involving chromosome 8p that eliminates the wildtype allele and results in two copies of the mutant FGFR1 allele in tumor cells." (PMID 32859279, 2020). "Moreover they showed that circulating tumor DNA from 34 patients progressing to the CDK4/6 drugs had amplifications or activating mutations of FGFR1 and FGFR2, which were as high as 41% in the patients." (PMID 32188012, 2020). "Notably, the predicted tumor content for two of these unclassifiable tumors was low, based on both microscopic assessment and also the FGFR1 p.K656E mutant allele frequencies being 10% for uLGNET #3 and 6% for uLGNET #4." (PMID 32859279, 2020). "Additionally, five tumors had trisomy (n = 4) or tetrasomy (n = 1) of chromosome 8, which includes the FGFR1 locus and resulted in extra copies of the mutant or rearranged allele in tumor cells." (PMID 32859279, 2020). "In addition to other clinicopathologic parameters, severe fibrosis was related to frequent tumor recurrence, and high FGFR1 expression was associated with better overall survival." (PMID 32171280, 2020). "Moreover, BGJ-398, a potent and selective inhibitor of FGFR1–4, completely suppressed tumor growth in a PDX model derived from an SDH-deficient GIST." (PMID 32392832, 2020). "The tumor harbored a double FGFR1 mutation (N546S and K656E) detected by sequencing." (PMID 31677015, 2020). "However, the predicted tumor content for the other three unclassifiable tumors was high, based on both microscopic assessment and FGFR1 mutant allele frequencies greater than 25%." (PMID 32859279, 2020). "Therefore, promoting inflammation in the tumor microenvironment is one of the mechanisms underlying the tumor promoting activity of FGFR1." (PMID 30761180, 2019). "It is unknown whether FGFR1 activation can further activate downstream signaling in breast epithelial and tumor cells with an active Ras mutation to promote these cell growth and progression to a more aggressive cancer cell phenotype." (PMID 30111373, 2018). "Clinical phase II trial (NCT01975701) targeting FGFR1-TACC1 and FGFR3-TACC3 fusions and/or activating mutation in FGFR1, 2, or 3 by anti-tumor drug BGJ398 has been completed in December, 2015 for assessment of overall survival, anti-tumor activity, and safety and tolerability." (PMID 29507709, 2018). "In addition, in vivo experiments performed on FGF-dependent models of prostate and lung cancer confirmed the capacity of NSC12 to inhibit FGFR1 activation and to reduce tumor growth and tumor-associated angiogenesis." (PMID 30349543, 2018). "In contrast, somatic mutations in tumor-promoting genes (FGFR1, RAC1, AFF3, AFF4, TSC2) may be intuitively associated with unfavorable prognosis." (PMID 30662871, 2018). "Furthermore, a weak association was observed between stronger FGFR1 staining and higher tumor proliferation index (p = 0.061, n = 68, Fisher’s exact test) among adult patients." (PMID 28468611, 2017). "However, FGFR1 staining was similarly associated with tumor location (p < 0.001, n = 70, Fisher’s exact test) and higher tumor grade (p < 0.01, n = 72, Fisher’s exact test) in the adult cohort as in the whole sample cohort." (PMID 28468611, 2017). "TCGA data, moreover, suggest that FGFR1 mutations are rare events (< 2%) in this tumor type." (PMID 26555375, 2015). "To evaluate whether the inhibition of tumor growth by Ad23 or Af23 was associated with the inhibition of FGFR1 activity in vivo, we analyzed the expression of p-FGFR1 in the tumor tissues." (PMID 25880284, 2015). "Taken together, these findings suggest that FGFR1 is associated with tumor recurrence and targeting the FGFR1 signaling pathway might prevent tumor relapse." (PMID 26581390, 2015).
tumor (continued). "Together, these findings suggest that SOX2 in part through upregulation of FGFR1 might enhance distant spreading of tumor cells to the liver, thereby causing a poorer patient survival." (PMID 25010701, 2014). "To assess whether the inhibition of tumor growth by Aea4- and Aea25 associated with the inhibition of FGFR1 in vivo, we studied the phosphorylation of FGFR1 in tumor tissue by western blot analysis." (PMID 24980830, 2014). "In addition, a genome-wide CRISPR activation screen revealed that fibroblast growth factor receptor 1 (FGFR1) signaling could compensate NRG1–HER3 axis function to rescue NRG1-deficient circulating tumor cells (CTCs)." (PMID 40129676, 2025). "This suggests similarity in gene expression between each tumor which may reflect the shared mutational profile, including activating FGFR1 variants, in addition to PIK3R1 variants predicted to activate the PI3K signaling pathway, in concert with the germline PTPN11 variant." (PMID 39309743, 2024). "OPCML exerts its tumor suppressor effect by inhibiting several cancer hallmark phenotypes in vitro, and abrogating tumorigenesis in vivo, by downregulating/inactivating a specific spectrum of Receptor Tyrosine Kinases (RTKs), including EphA2, FGFR1, FGFR3, HER2, HER4, and AXL." (PMID 36835855, 2023). "However, all SLs examined had the same FGFR1 mutation as the mother tumor." (PMID 36639714, 2023). "Thus, BRAF and FGFR1 mutations would be secondary driver events in the oncogenesis of these tumours and could give a proliferative advantage to the H3.3-K27M ancestral clone in a specific developmental window similarly to paediatric LGGs." (PMID 38066305, 2023). "Theoretically, the case here presented could benefit the most from such treatment, being carrier of two mutations in this cascade, with the somatic PTPN11 variant affecting part of the body—including tumor tissue—and a variant in FGFR1 detected only in tumor tissue." (PMID 35778969, 2022). "We observed a delay in tumor appearance in all mice injected with FGFR1-deficient cells and these cells grew at a slower rate than FGFR1-competent cells regardless of treatment, suggesting the FGFR1 signaling contributed to tumor cell growth in the mammary fatpad." (PMID 33916323, 2021). "Having taken a novel and unbiased approach to classification, our findings suggest that BRAF and FGFR1 mutations are highly specific within glioneuronal tumours to each of the two molecular tumour groups we have identified, and may be well suited as markers for distinguishing them from one another." (PMID 29058119, 2018). "In that preclinical tumor models with high FGFR1 expression, 18F-FGFR1 exhibited excellent stability, specificity, and contrast, enabling effective visualization of FGFR1-expressing lesions with minimal off-target accumulation." (PMID 41584352, 2026). "In ER-positive breast cancer, co-treatment with DGY-09-192 and the ERα degrader fulvestrant led to complete inhibition of cell proliferation and significant tumor regression in ER-positive, FGFR1-amplified patient-derived xenograft models." (PMID 41584352, 2026). "In high-grade diffuse gliomas (HGG), aberrant FGFR1 splicing cooperates with NF1 splicing alterations to enhance tumor aggressiveness." (PMID 41584352, 2026). "By targeting both angiogenic and oncogenic pathways, including FGFR1, regorafenib contributes to tumor microenvironment modulation and offers a therapeutic advantage in malignancies with activated FGFR1-2 signaling." (PMID 41226200, 2025). "In the MONALEESA‐2 trial of ribociclib, circulating tumor DNA (ctDNA) analysis revealed that patients with FGFR1 amplification had shorter PFS than those carrying wild‐type FGFR1." (PMID 41049266, 2025).
tumor (continued). "By inhibiting FGFR1 signaling, pemigatinib attenuates tumor cell proliferation, angiogenesis, and resistance mechanisms in FGFR-driven malignancies, including cholangiocarcinoma and urothelial cancers." (PMID 41226200, 2025). "Research demonstrates that FGFR expression remains more stable in highly aggressive tumors, and FGFR3 overexpression or aberrant activation of other FGFR family members (e.g., FGFR1) can promote tumor progression and metastasis via ligand-dependent mechanisms." (PMID 41438986, 2025). "Given the pivotal role of FGFR1 in tumor biology and immune evasion, targeting FGFR1 represents a promising approach to enhance the efficacy of immunotherapy." (PMID 40547805, 2025). "The resulting truncated FGFR1 protein retains oncogenic activity, driving tumor growth in experimental models." (PMID 40393028, 2025). "FGF11 activates the FGFR1 signaling pathway in adjacent tumor cells, forming a pro-tumorigenic feedback loop that promotes tumor proliferation and stemness." (PMID 41002423, 2025). "Our recent research has brought to light the relatively rare N546K mutation in the FGFR1 gene, which activates downstream signaling pathways, culminating in an aggressive tumor phenotype and resistance to FGFR1 inhibitors." (PMID 39843641, 2025). "FGFR1 involvement in angiogenesis is also significant, as it further contributes to tumor proliferation and the spread of metastases." (PMID 40547805, 2025). "The FGF/FGFR1/NOTCH1 within RB1 variant group has a dramatically inflamed microenvironment, showing higher inner‐tumor CD8+ T cell infiltration." (PMID 40001320, 2025). "Numerous sequencing studies have revealed a wide range of FGFR1 abnormalities across tumor patients, with prevalence rates spanning 1.9% to 98%." (PMID 40547805, 2025). "The progression of PCa is likely influenced by the interplay of these targets where FGFR1 drives tumor growth and metastasis, MMP-9 facilitates invasion, and PDGFRB promotes tumor growth and angiogenesis." (PMID 40429793, 2025). "Identifying PDGFRA or PDGFRB rearrangements is critical, as imatinib effectively treats these conditions, whereas pemigatinib is approved for refractory FGFR1-rearranged neoplasms." (PMID 40508151, 2025). "P03 also has mutations in MTOR and ELF3, while P04 has mutations in FGFR1, and P05 has mutations in PIK3CA and NTRK1–genes involved in tumor growth and survival." (PMID 41012124, 2025). "FGFR1 inhibition not only enhances radiosensitivity but also downregulates key effectors such as S100A4, which are associated with tumor stemness, mesenchymal transition, and microenvironmental modulation." (PMID 41002392, 2025). "It suppressed tumor proliferation by downregulating fibroblast growth factor receptor 1 (FGFR1) phosphorylation or activating the ROS-mediated NF-κB pathway, positioning HA as a promising PDT photosensitizer for cancer treatment." (PMID 41157077, 2025). "In this case, the development of HPD was associated with a high postoperative tumor burden, elevated PD-1 expression, and aberrant activation of signaling pathways mediated by EGFR, MET, and FGFR1 amplifications." (PMID 40575167, 2025). "Upon anti-PD-1 treatment, tumors demonstrate hyperprogression, which can be attributed to the abundance of Treg cells within the tumor microenvironment; erdafitinib treatment can reverse this by targeting FGFR1 on the Treg cell surface." (PMID 40603902, 2025). "FGF9 gene, which encodes a ligand for multiple FGFRs, including FGFR1 and FGFR2, is expressed by stromal cells in NB tumours." (PMID 41511287, 2025). "The study suggested that TGF-β/SMAD–induced acetylation of KLF5 acts as a barrier to tumor progression, in part by restraining excessive FGFR1 signaling." (PMID 41514658, 2025).